CDKN2A (cyclin dependent kinase inhibitor 2A)
Diseases named in the same sentence as CDKN2A in open-access papers (continued):
Sharing a sentence is not in itself a finding about the gene and the disease.
melanoma (continued). "Inactivation of CDKN2A is present in up to 90% of all melanomas and usually occurs when a melanoma becomes invasive." (PMID 35008286, 2021). "It has long been known that the atypical nevus count correlates with the common nevus count, and more recently, the role of the CDKN2A locus in the development of histological atypia in nevi during melanoma progression was proposed." (PMID 34356093, 2021). "While the relationship between melanoma and CDKN2A is well known, information on the involvement of the CDKN2A gene in leukemia predisposition is scarce." (PMID 34771502, 2021). "A large number of genes have been identified as hypermethylated in melanoma, including O6-methylguanine-DNA methyltransferase (MGMT), cyclin-dependent kinase inhibitor 2A (CDKN2A), and Ras-association domain family 1 isoform A (RASSF1A)." (PMID 34944843, 2021). "We did not observe differences in normalized log10 gene expression levels between controls, CDKN2A mutant or CDKN2A wild-type familial melanoma patients." (PMID 34660619, 2021). "Copy number variants, including loss of CDKN2A and gain of KIT, CDK4 and MYC, were frequently seen in mucosal melanomas." (PMID 34571863, 2021). "For instance, approximately 50–60% of melanoma patients have the BRAFV600E driver mutation, 60% have inactivating CDKN2A mutations and 5–20% have inactivating PTEN mutations." (PMID 34064795, 2021). "Current guidelines for clinicians managing individuals tested positive for CDKN2A germline P/LPV are directed towards surveillance for melanoma and pancreatic cancer." (PMID 33766116, 2021). "The international guidelines developed in 2009 suggest patients be tested for CDKN2A based on the following: number of primary melanomas in the patient, melanomas in blood relatives, and pancreatic cancer in the patient or blood relatives." (PMID 34638397, 2021). "Presently, clinical genetic testing for CDKN2A is indicated for individuals with multiple primary melanoma and/or a family history of melanoma or pancreatic cancer." (PMID 33766116, 2021). "The combination of CCND1 amplification and CDKN2A loss or CDK4/6 mutations has been associated with resistance mechanisms and shorter progression free survival in patients with BRAF-driven melanoma treated with BRAFi." (PMID 34066022, 2021). "Loss of both cyclin-dependent kinase inhibitor 2A (CDKN2A) alleles and the occurrence of genomic copy number alterations are also possible in invasive melanomas." (PMID 34440462, 2021). "PV in 10 PDAC patients with multiple primary tumors affected 3 × BRCA1 and 4 × BRCA2 (all had also developed breast and/or ovarian cancer), 1 × PMS2 and 1 × MLH1/MSH6 (both developed colon cancer), and 1 × CDKN2A (diagnosed with melanoma)." (PMID 34503238, 2021). "Melanomas are most frequently characterized by BRAF and NRAS mutation and, more rarely, by c-KIT oncogene mutations, but tumor suppressor genes such as CDKN2A and PTEN have an important role in the development and prognosis of melanoma." (PMID 34209415, 2021). "Here we show that the embryonic stem cell (ESC) factor Sall4 is re-expressed in the Tyr::NrasQ61K; Cdkn2a−/− melanoma model and that its expression is necessary for primary melanoma formation." (PMID 34417458, 2021). "Alterations of the complete CDKN2A locus are identified in approximately 30% of human tumors, including glioblastoma, pancreatic cancer, adenocarcinoma, and melanoma." (PMID 33445626, 2021).
melanoma (continued). "Healthcare professionals caring for CDKN2A carriers should have a heightened index of suspicion for malignancies beyond melanoma and pancreatic cancer." (PMID 33766116, 2021). "CDKN2A and its binding partner CDK4 were the first melanoma genes to be identified as melanoma-predisposing genes, though mutations in these loci have only been found in 20–45% of familial melanoma cases." (PMID 34356093, 2021). "MITF plays a critical role in melanocyte development and melanoma carcinogenesis by controlling the expression of several melanoma-associated genes that regulate proliferation and invasion, including MET5 and CDKN2A/p16INK4A5." (PMID 34503213, 2021). "Due to the different genetic backgrounds of melanoma cell lines, we adopted RNAi treatmet to knockdown CDKN2A expression in CDKN2AWT cell line A2058." (PMID 33627666, 2021). "Cyclin-dependent kinase inhibitor 2A (CDKN2A), the first known melanoma susceptibility gene, is located on chromosome 9 (9p21.3)." (PMID 34711012, 2021). "CDKN2A promoter hypermethylation occurs in uveal melanoma and cutaneous melanoma; p14ARF expression is inversely correlated with melanoma progression since its expression decreases in the progression from melanocytic nevi to the metastatic state." (PMID 34944799, 2021). "Melanoma patients diagnosed at a younger age tend to have a higher frequency of CDKN2A somatic alterations, however, with 72% of patients aged 30 years or younger displaying melanoma-associated CDKN2A alterations, and this diminishes with increasing age." (PMID 33076392, 2020). "In this review, we examine genetic alterations affecting the CDKN2A locus in melanoma, the functional impact of altered CDKN2A, and the contribution of this locus to melanoma development and progression." (PMID 33076392, 2020). "Numerous genes have been associated with melanoma: beyond CDKN2A and CDK4, primarily included as high-risk genes for familial melanoma, BAP1, POT1, and MITF were recently also identified as potential high-risk melanoma susceptibility genes." (PMID 33322357, 2020). "In particular, mutation occurring in the cyclin-dependent kinase inhibitor 2A (CDKN2A) and cyclin-dependent kinase 4 (CDK4) genes are the most frequent genetic abnormalities associated with melanoma risk." (PMID 32392801, 2020). "These include genes predominantly associated with melanoma (such as CDKN2A and CDK4) but also genes related to multiple solid tumors including melanoma." (PMID 33167923, 2020). "One report described a melanoma with GOLGA4 fused to exons 8–17 of RAF1, retaining the RAF1 kinase domains, and with accompanying mutations in CTNNB1 and CDKN2A." (PMID 32123303, 2020).
melanoma (continued). "For instance, somatic mutations in CDKN2A and BRAF are commonly found in the sporadic form of melanoma." (PMID 32169117, 2020). "In particular, 50% of melanoma patients aged 31–50, 41% of patients aged 51–70, and 36% of patients aged > 71 had somatic CDKN2A genetic changes." (PMID 33076392, 2020). "The majority of CDKN2A alterations in melanoma selectively target p16INK4a or affect the coding sequence of both p16INK4a and p14ARF." (PMID 33076392, 2020). "In this review, we describe the frequency and types of somatic alterations affecting the CDKN2A locus in melanoma and germline CDKN2A alterations in familial melanoma, and their functional consequences in melanoma development." (PMID 33076392, 2020). "Inactivation of the CDKN2A locus has been detected in approximately 50% of primary melanomas and over 75% of metastatic melanomas." (PMID 33076392, 2020). "The majority of CDKN2A alterations in melanoma selectively target p16INK4a or affect the coding sequences of both p16INK4a and p14ARF." (PMID 33076392, 2020). "In order to assess the impact of SK1 expression on melanoma growth, we generated stable SK1 knockdown cells using Yumm 1.7 cells derived from spontaneous murine melanoma driven by Braf activation, as well as Pten and Cdkn2a inactivation." (PMID 31974367, 2020). "While CDKN2A, BRCA1 protein, and CDK4 genes are known susceptibility genes that are considered to be high risk for melanoma, a well-established clinical utility for testing these gene must first be established." (PMID 33339193, 2020). "Already before the rise of GWAS, deletions of the ANRIL lncRNA gene upstream of the CDKN2A and CDKN2B genes have been associated with increased risk of melanoma and neural system tumor development in several families (see section Amplifications and Deletions)." (PMID 33329688, 2020). "Recent studies have led to the identification of new genes involved in CMM susceptibility: beyond CDKN2A and CDK4, BAP1, POT1, and MITF were recently identified as potential high-risk melanoma susceptibility genes." (PMID 33322357, 2020). "The loss of the CDKN2A sequence also co-operates with the BRAF and NRAS oncogenes to promote melanoma development." (PMID 33076392, 2020). "Until a few years ago, CDKN2A/ARF (cyclin dependent kinase inhibitor 2A) and its binding partner CDK4 (cyclin dependent kinase 4) were the only known melanoma-predisposition genes tested in clinical practice." (PMID 32325837, 2020). "Large germline CDKN2A deletions encompassing exon 1α, 2, and/or 3 which affect both p14ARF and p16INK4a have also been identified in melanoma-prone kindreds, although these are uncommon and account for only 2% of germline CDKN2A alterations." (PMID 33076392, 2020). "Both A375 and RPMI7951 melanoma cells bear the BRAF mutation (p.V600E) and CDKN2A mutation, however, only A375 cells harbor a homozygous mutation in the BRAF gene." (PMID 33114713, 2020).
melanoma (continued). "These mutation frequencies are consistent with previous reports and confirm that homozygous CDKN2A deletions are the most common alterations affecting this locus in melanoma." (PMID 33076392, 2020). "Other genes including CDKN2A, CDK4, BAP1, POT1, ACD, TERF2IP, and TERT are known for their high penetrance as predisposing mutations for melanoma." (PMID 33339193, 2020). "They finally proposed a new solution that adding 9p21 (CDKN2a) into previous 4-probe FISH assay for spitzoid melanomas diagnosis." (PMID 32210733, 2020). "ANRIL silencing was able to restore the proper expression of CDKN2A and B in a melanoma xenograft model." (PMID 30499222, 2019). "Both CDKN2A and CDK4 represent high-susceptibility genes for malignant melanoma, i.e., mutation in such genes greatly increases the chance of melanoma development." (PMID 31717496, 2019). "Many of the SV events targeted well-known melanoma driver genes (CDKN2A, NF1, PTEN, and TERT), exemplifying their role in mucosal melanoma pathogenesis." (PMID 31320640, 2019). "We compared detection of the most frequent deletion in melanoma (CDKN2A) to data generated using MLPA as a high sensitivity method." (PMID 31222134, 2019). "CDKN2A deletions have been recognized as an adverse prognostic marker in a number of tumors, i.e. in melanoma." (PMID 30809375, 2019). "The development of melanoma often involves mutations in BRAF, CDKN2A, CCND1, INK4A, and MAPK signaling pathway components, many of which are also important for the development of neural crest-derived melanocytes." (PMID 31569501, 2019). "Alterations of the CDKN2a locus were found in roughly 30% of human tumors such as glioblastoma, melanoma and pancreatic adenocarcinoma." (PMID 30836703, 2019). "The YMR1.7 line was generated by UVB irradiation of YUMM (YM) 1.7 murine melanoma cell line, which was derived from tumor arising in a BrafV600E, Pten−/−, and Cdkn2a−/− mouse model of melanoma." (PMID 31601678, 2019). "This is consistent with the findings demonstrating a progressive inactivation of the CDKN2A tumor suppressor gene during melanoma progression, which in turn promotes uncontrolled cell proliferation, tumor growth, and increased aggressiveness of tumor cells." (PMID 29492214, 2018). "The carrier of g.124510982 G>A, was a male patient, diagnosed with an amelanotic melanoma at the age of 33 with a second melanoma excised 35 years later and was tested wild type for CDKN2A." (PMID 29523635, 2018). "A cross-sectional study was conducted by genotyping CDKN2A/CDK4 variants and selected MC1R polymorphisms in 52 melanoma-prone families." (PMID 29774366, 2018). "One of the clearer examples of DNA methylation, affecting the apoptotic program in melanoma, is the silencing of CDKN2A locus, encoding for the tumor suppressor genes, p16INK4A and p14ARF." (PMID 29371600, 2018). "Two high-penetrance genes, CDKN2A and CDK4, both regulators of the cell cycle, have been first evidenced in around 20% of the families predisposed to melanoma." (PMID 29963229, 2018). "The Cyclin-dependent kinase inhibitor 2A (CDKN2A) mouse model has been widely used to investigate the effect of genetic alterations in melanoma initiation, progression and metastasis." (PMID 30544544, 2018). "In our series, occurrence of CDKN2A gene alterations in melanoma tissues and cell lines appears to consistently increase moving from primary tumors to metastases till to cultured melanoma cells." (PMID 29492214, 2018).
melanoma (continued). "On the other hand, the loss of miR-204 was enriched in melanomas with NRAS sole mutation (Fisher exact test, P = 0.001, Log Odds = 1.67), and less frequent than expected in those harbouring CDKN2A mutations (Fisher exact test, P = 0.001, Log Odds - 1.09)." (PMID 29523154, 2018). "For example, a point mutation introducing a uORF in the 5′ UTR of CDKN2A decreases cyclin-dependent kinase inhibitor 2A (CDKN2A) protein level and causes melanoma." (PMID 30028832, 2018). "Cyclin-dependent kinase inhibitor 2A (CDKN2A), located on 9p21 locus, is a well-established tumor suppressor that was frequently inactivated in multiple human tumors, including melanomas, glioblastomas, pancreatic cancers, bladder cancers and the like." (PMID 29904067, 2018). "The aims of this study were to report the incidence of CDKN2A and CDK4 variants in a series of Greek familial melanoma families and to examine their association with epidemiological and clinical factors, as well as MC1R polymorphisms." (PMID 29774366, 2018). "25–50% of familial MM relatives display a mutation in CDKN2A and variants in MC1R are common in the white population, conferring low to moderate risk to develop melanoma." (PMID 29998107, 2018). "One example is the high incidence of methylation found in critical genes of melanoma samples, specifically the hypermethylation of CDKN2A that silences the expression of protein p16." (PMID 29740318, 2018). "This region contains the CDKN2A gene, which has a well-characterized role in cell cycle regulation and is responsible for a substantial proportion of familial melanomas." (PMID 28973033, 2017). "CDKN2A deletions have frequently been found in melanoma and lung cancer brain metastases, suggesting a potential role of RB pathway inactivation and metastatic diffusion to the brain." (PMID 28445153, 2017). "CDKN2A is a tumor suppressor/negative regulator in the CDK4/Rb pathway, and is frequently lost and/or mutated in melanoma, pancreatic cancers, and other tumor types." (PMID 28749946, 2017). "Of the genes with known amplifications and deletions in melanoma, the CDKN2A locus showed a considerable deletion frequency." (PMID 29170503, 2017). "A CSD UV signature is typically found in melanoma tumor suppressors such as CDKN2A resembling the exome average." (PMID 28265786, 2017). "The melanoma predisposition due to a single gene knockout is comparable to deleterious germline variants in a number of genes such as CDKN2A and POT1 that have been shown to underlie familial melanoma cases in human patients." (PMID 28806732, 2017). "There, a novel uAUG in CDKN2A led to decreased translation from the wild‐type AUG and to predisposition to melanoma." (PMID 28546996, 2017). "We also used a novel mouse model of melanoma to demonstrate that several of these MEK mutants promote the development, growth and maintenance of melanoma in vivo in the context of Cdkn2a and Pten loss." (PMID 28263969, 2017). "In melanoma-dominant or melanoma-subordinate pedigrees or in individuals carrying a BAP1, CDK4, CDKN2A, MITF, or POT1 mutation, individuals should be educated on the importance of melanoma prevention and early detection." (PMID 28283772, 2017). "We also uncovered a significant association in the CDKN2A/MTAP region, previously reported in two separate GWAS of melanoma in Caucasians." (PMID 28973033, 2017). "Having mutations in of CDKN2A and CDK4 is associated with a significant increased risk of malignant melanoma." (PMID 27804060, 2017).